ESM1 (endothelial cell specific molecule 1)
Diseases named in the same sentence as ESM1 in open-access papers (continued):
Sharing a sentence is not in itself a finding about the gene and the disease.
infection (2 papers, 2021 to 2023). The state of being infected such as from the introduction of a foreign agent such as serum, vaccine, antigenic substance or organism. "The differential expression of esm1, stil, and pbk between pre- and post- vaccination samples was readily observed, especially the change in expression between animals that survived through the end of the experiment at 14 weeks and those that succumbed to infection early." (PMID 37535648, 2023). "Our results showed that BAE cell infection by E. ruminantium resulted in the over-expression of several ECs surface proteins, such as ICAM1, VCAM1, CSF1, ESM1 and MCAM." (PMID 34073568, 2021).
bacterial infection (1 paper, 2023). "In addition, Kazunori and colleagues found that ESM-1 levels were elevated at the onset of the bacterial infection but subsequently reduced." (PMID 37161496, 2023).
inflammation (1 paper, 2023). Aberrant reaction of the microcirculation characterized by movement of fluid and leukocytes from the blood into extravascular tissues. "Indeed, the continuous infusion of murine glycosylated endocan in the Esm1−/− mice led to an alleviation of lung inflammation associated with an improvement in pulmonary physiological function when compared with the Esm1−/− mice treated with PBS." (PMID 36672192, 2023).
prostate (1 paper, 2017). "The aim of this work was to analyze the expression profile of CXC-chemokines and the effects of ESM-1 gene knockdown in proliferation, migration and CXC-chemokine expression in highly metastatic human prostate PC-3 cells." (PMID 28533735, 2017). "The aim of this study was to analyze the expression profile of CXC-chemokines and the effects of ESM-1 gene knockdown in proliferation, migration and CXC-chemokine expression in highly metastatic human prostate PC-3 cells." (PMID 28533735, 2017).
ESM1 also shares sentences with these, for which no sentence is quoted: acute coronary syndrome (2 papers); adenocarcinoma (2); erectile dysfunction (2); kidney diseases (2); type 2 diabetes (2); vascular disorder (2); acute leukemia (1); acute lung injury (1); Ascites (1); benign tumor (1); bladder urothelial carcinoma (1); breast tumor (1); cardiomyopathies (1); cerebral edema (1); chronic fatigue syndrome (1); chronic pancreatitis (1); colon adenocarcinoma (1); dengue (1); diabetic nephropathy (1); encephalomyelitis (1); endocervical adenocarcinoma (1); keloid (1); lactic acidosis (1); laryngeal squamous cell carcinoma (1); liposarcoma (1); liver cirrhosis (1); lung adenocarcinoma (1); lung injury (1); mesothelioma (1); metastasis (1).
A further 15 diseases each share a sentence with ESM1 in 1 paper.